NRP1 (neuropilin 1)
Diseases named in the same sentence as NRP1 in open-access papers (continued):
Sharing a sentence is not in itself a finding about the gene and the disease.
lung carcinoma (continued). "In a recent study, two siRNAs of snail family zinc finger (SLUG) and neuropilin-1 (NRP1) which are known to be important transcriptional factors in the activation of key signaling pathways were successfully carried into lung cancer cells by an anti-nucleolin aptamer." (PMID 26863567, 2016). "Small interfering RNAs have also been utilized to target NRP-1, resulting in a significant reduction of the growth, angiogenesis and metastasis formation in various human tumor models, such as hepatocellular carcinoma, acute myeloid leukemia, and lung cancer." (PMID 26090340, 2015). "In two different lung cancer cell lines, hypoxia regulated NRP1 expression differently." (PMID 24977165, 2014). "Moreover, they showed that Nrp1 knockdown in lung cancer cell lines reduced their ability to migrate, invade and form filipodia, and it also inhibited metastasis." (PMID 22948112, 2012). "This drug inhibited VEGF-A binding to NRP1, and reduced the viability of A549 lung carcinoma cells." (PMID 22948112, 2012). "In agreement with NRP1 antagonism, NRP1 silencing with two individual specific siRNAs in lung carcinoma A549 cells decreased cell viability and increased the cytotoxic effects of both 5-FU and paclitaxel as compared with that in control siRNA-transfected cells." (PMID 20087344, 2010). "Thus, dual-target PLK1/NRP1 inhibitor (PLN-5) may represent a potential therapeutic strategy in lung cancer." (PMID 40820676, 2025). "However, the molecular mechanism through which NRP1 plays a crucial role in the formation of radiation resistance in lung cancer cells is unknown; in particular, more research into transcription factor regulatory mechanisms is needed." (PMID 35993027, 2022). "In addition, expression of NRP1 is correlated with poor prognosis in various types of tumor, including lung cancer, colon cancer, ovarian cancer, and prostate cancer, implying that NRP1 could be a potential molecular target for treatments of tumor." (PMID 32408477, 2020). "It was thus confirmed again that NRP1 could induce radiation resistance in lung cancer cells." (PMID 31417646, 2019). "First, we determined whether troglitazone affects the expression of VEGF-A and its receptors, fms-like tyrosine kinase (FLT-1/VEGFR1), kinase insert domain receptor 1 (KDR/VEGFR2), and neuropilin-1 (NRP-1) in the human lung cancer cell lines, RERF-LC-AI, SK-MES-1, PC-14, and A549." (PMID 20214829, 2010). "In the hypoxic microenvironment of lung cancer (LUAD), HIF-1α transcriptionally upregulates NRP1 expression by directly binding to the NRP1 promoter region (−2009 to −2017 bp)." (PMID 41019994, 2025). "This interaction reduces the miRNA silencing activity toward its downstream targets, i.e., the mRNAs coding for GLUT1, NRP1, YY1, and Wnt5a, thus contributing to oncogenic pathways driving lung cancer." (PMID 38672608, 2024). "In breast and lung cancer cells, activation of TGFBR triggered by overexpression of neuropilin-1 leads to increased Smad2/3 activation, which is inhibited when neuropilin-1 is silenced." (PMID 38351317, 2024). "As indicated in the Results section, we evaluated those targets in our experimental system and found that GLUT1, NRP1, YY1, and Wnt5a were effectively inhibited by the miRNA in lung cancer cells." (PMID 38672608, 2024). "As the endothelial codepletion of NRP1 and NRP2 was found to effectively impair primary lung carcinoma growth and angiogenesis, we proceeded to assess the efficacy of their codepletion in other paradigms of cancer." (PMID 36970722, 2022). "Other research revealed that CALR regulated EMT through modulating Smad signaling and calcium signaling in lung cancer cells and via TGF-β/Smad3/NRP1 pathway in nasopharyngeal carcinoma cells." (PMID 35641480, 2022). "The tLyp-1 peptide is able to bind to receptors such as neuropilin-1 (NRP1) and neuropilin-2 (NRP2), which are overexpressed on the surface of lung cancer cells." (PMID 35765040, 2022).
lung carcinoma (continued). "Our work makes a comprehensive evaluation of NRP1 and TMPRSS2 in lung cancers, providing information for drug development and support for COVID-19 patients with lung cancers." (PMID 34168096, 2021). "ACE2 barely shows any interaction in LUAD, LUSC, STAD or PRAD, but NRP1 and TMPRSS2 have multiple interactions in LUAD and LUSC, indicating significant roles of NRP1 and TEMPRSS2 in lung cancers." (PMID 34168096, 2021). "Here we show that Nrp-1 defines a subset of CD8+ T cells displaying PD-1hi status and infiltrating human lung cancer." (PMID 31350404, 2019). "Neuropilins (NRP1 and NRP2) are overexpressed in several cancers, and their expressions correlate with increased invasion and poor prognostic in lung cancer." (PMID 28804523, 2017). "Neuropilin-1 (NRP1), a non–tyrosine kinase receptor, is overexpressed in many cancers including pancreatic and lung cancers." (PMID 29018205, 2017). "To understand the differential role of NRP1 in different cancers, we utilized short-hairpin RNA (shRNA)-mediated NRP1 knockdown in human pancreatic cancer (PDAC) and non–small cell lung cancer (NSCLC) cell lines." (PMID 29018205, 2017). "Comparison of neuropilin-1 (NRP-1) and neuropilin-2 (NRP-2) expression on alveolar macrophages in lung cancer adjacent to the cancer margin, lung inflammation and lung tissue remote to the cancer nest (physiologically normal lung)." (PMID 26900851, 2016). "We have previously demonstrated abrogation of aberrant tyrosine kinase activity, as well as enhanced NRP-1 trafficking and degradation by LKB1 in lung cancer cells." (PMID 26701889, 2016). "EG00229 inhibited VEGF-A binding to NRP-1, decreased VEGFR-2 phosphorylation and the migration of lung carcinoma cells in vitro." (PMID 26090340, 2015). "Coexpression of NRP1 and NRP2 also increases in the progression from dysplasia to microinvasive lung carcinoma, and correlates significantly with tumour progression and poor prognosis in patients with non-small-cell lung carcinoma." (PMID 20087344, 2010). "Finally, the ability of JPX to inhibit the silencing activity of miR-378a-3p toward its targets GLUT1, NRP1, YY1, and Wnt5a, and thus the contribution to lung cancer, was demonstrated." (PMID 38672608, 2024). "Additionally, lung adenocarcinoma cells from NSCLC, the most frequent form of lung cancer, were selected to verify that YAP/TEAD4/NRP1 had an effect on radiation resistance in NSCLC cells but other lung cancer classification have not been well explored." (PMID 39187525, 2024). "NRP1 regulation of radioresistance in lung cancer involves downstream homeobox genes HOXA6 and HOXA9, and microRNA-9 is able to restore radio-sensitivity in radioresistant lung cancer cells by targeting NRP1." (PMID 37894289, 2023). "In addition, NRP1 levels predict the efficacy of MET oncogene inhibitors in stomach and lung carcinoma cells." (PMID 37894289, 2023). "Moreover, we confirmed the positive relationship between NRP1, HIF-1α, and VE-cadherin expression in lung cancer tissues via the public GEPIA, UCSC, and CCLE databases." (PMID 33850110, 2021). "Despite its significant role in immune system, the onco-immunity role of NRP1 in lung cancers has never been studied." (PMID 34168096, 2021). "Interestingly, NRP-1 has also been reported to contribute to TGF−β−induced EMT and metastasis of non−small cell lung cancer cells by binding with TGFβRII." (PMID 33912463, 2021). "NRP-1 and NRP-2 expression increased in AMs under conditions of lung inflammation and lung cancer." (PMID 26900851, 2016). "NRP-1 and NRP-2 were expressed in AMs in lung cancer patients both with and without smoking habits." (PMID 26900851, 2016). "NRP-1 and NRP-2 expression was also observed in some lung cancer cells (data not provided)." (PMID 26900851, 2016).
glioblastoma (57 papers, 2009 to 2025). The most malignant astrocytic tumor (WHO grade IV). "NRP1 is also highly expressed in glioblastoma multiforme (GBM) and is closely associated with the prognosis of GBM patients." (PMID 35686121, 2022). "Importantly, higher tumoral NRP1 mRNA content in glioblastoma (GBM) is associated with a worst patient prognosis." (PMID 37894289, 2023). "Elevated Nrp1 expression is a risk factor for glioblastoma recurrence and shorter patient survival." (PMID 29642487, 2018). "For example, the KDKPPR peptide has recently been combined with a photosensitizer and a contrast agent to bind NRP1 for the detection and treatment by photodynamic therapy of glioblastoma, an aggressive brain cancer." (PMID 37513474, 2023). "Here, we review NRP1 expression and function in adult and pediatric brain cancers, particularly glioblastomas (GBMs) and medulloblastomas, and present analyses of NRP1 transcript levels and their association with patient survival in GBMs." (PMID 37894289, 2023). "This role of NRP1 in the sensitivity of cancer stem-like cells has been recently shown in glioblastoma multiform treated with chemotherapy (temozolomide) by using knockdown models." (PMID 36457009, 2022). "Corroborating this study, Nrp1 expression was shown to be significantly correlated with the expression of ionized calcium binding adaptor molecule 1 (Iba1) and CD11b in a glioblastoma patient cohort." (PMID 36203599, 2022). "The role of NRP1 in glioblastoma has been mainly explored in the context of endothelial cell biology, in response to VEGF, Class III Semaphorins, and integrins." (PMID 36204684, 2022). "Anatomical annotations of relative Nrp1 expression in glioblastomas illustrated that its expression was detected specifically in areas of hyperplastic blood vessels and areas of microvascular proliferation." (PMID 36203599, 2022). "This work has shown that the ablation of NRP1 appears to improve the therapeutic response in glioblastomas." (PMID 34277411, 2021). "The use of temozolomide (TMZ) in combination with inhibition of VEGFR signaling appears to have beneficial effects in the treatment of glioblastomas as TMZ has been shown to reduce the expression of NRP1 and thus induce an increase in treatment cytotoxicity." (PMID 34277411, 2021). "Recently, a study on glioblastomas has shown that Sema 3C, secreted by glioblastoma stem cells, forms a complex with PlexinA2/D1 and NRP1, promoting glioblastoma self-renewal and sphere formation." (PMID 34277411, 2021). "Autocrine VEGF/VEGFR signaling was found to be enhanced by interaction with NRP1 in glioblastoma multiforme, while in NSCLC NRP1 overexpressing tumor cells exhibited significantly increased tumor growth." (PMID 33121034, 2020). "In glioblastoma multiforme, miR-124-3p acts as a suppressor of NRP1, which promotes tumor cell proliferation and migration as well as tumor angiogenesis via PI3K/AKT/NFκB signaling." (PMID 30717262, 2019). "We previously showed that the disruption of the NRP1/Plexin-A1 dimer suppresses vascular endothelial growth factor type A (VEGFA)-induced migration of glioblastoma U-118MG cells." (PMID 31652529, 2019). "In TCGA glioblastoma samples, the median NRP1 expression was significantly increased versus levels in normal brain (note: low n for normal brain tissue); moreover, NRP1 levels appeared to further increase upon tumor recurrence." (PMID 31208428, 2019). "U87MG human glioblastoma cells, which express NRP1 and were used previously specifically in this assay, were transfected to overexpress miR126-5p or miR142 as a control." (PMID 29773756, 2018). "This vascular leakage, at least in part, derives from the pro-permeability factor Semaphorin3A (Sema3A) produced within the glioblastoma, which triggers endothelial barrier permeability most commonly via engaging its receptor Neuropilin 1 (NRP1)." (PMID 29960602, 2018).
glioblastoma (continued). "Temozolomide, the standard chemotherapy for glioblastoma, induces apoptosis of glioblastoma cell lines in part through downregulation of Nrp1, and temozolomide synergizes with anti-angiogenic treatment to further induce cell death." (PMID 29642487, 2018). "As previously shown by us a peptide targeting the TMD of neuropilin-1 (MTP-NRP1), blocks cell proliferation, cell migration and angiogenesis in vitro, and decreases glioblastoma growth in vivo." (PMID 27351129, 2016). "In the present study, VEGF-A induced the cancer cell proliferation of PC3M (prostate cancer), DJM-1 (skin cancer), and U87MG (glioblastoma cell) in an anchorage-independent manner via the NRP1 signaling pathway." (PMID 26209534, 2015). "NRP1 siRNAs or anti-NRP1 peptides have been shown to inhibit tumor growth, angiogenesis and metastasis in several cancers including hepatocellular carcinoma and glioblastoma." (PMID 26097868, 2015). "Likewise, glioblastoma-associated LM and PC/PV CAMs exhibited hypoxia-responsive traits, with FTL and NRP1 (encoding CD304) upregulation." (PMID 38123840, 2024). "We hypothesized that the nanoparticle targeted to neuropilin-1 and combined with a photosensitizer of high efficiency of singlet oxygen generation would be effective against endothelial and glioblastoma cells leading to tumor damage." (PMID 39682113, 2024). "NRP1 is also highly expressed in neuronal cells and olfactory epithelium, thus contributing to the SARS-CoV-2 entering the central nervous system, causing a pathological complication, and enhancing the deterioration of glioblastoma or brain tumors." (PMID 38138098, 2023). "More recently, a study of patient-derived glioblastoma multiforme xenografts in zebrafish and mouse models have reported that depletion of NRP1 inhibits the growth of the tumor and substantially prolongs the survival rate of mice in comparison with VEGF-depletion, by improving sensitivity to TMZ." (PMID 34277411, 2021). "Another study suggested that NRP1, in combination with Plexin-A1, was correlated with poor prognosis in glioblastomas and may contribute to tumor growth." (PMID 34277411, 2021). "In attempt to destroy glioblastoma, which is the most frequent and malignant brain tumor, several peptides were developed by our team and other groups that successfully targeted NRP-1." (PMID 31847227, 2019). "Neuropilin-1 (NRP-1) is a co-receptor of vascular endothelial growth factor receptors (VEGFR) localized not only on angiogenic endothelial cells but also onto tumoral cells such as glioblastoma cell lines (U87)." (PMID 31847227, 2019). "Western blot analysis showed downregulation of full length NRP1 protein (120 kDa isoform) on miR-148a expression in multiple cell lines including Daoy, D283, medulloblastoma cell lines and U373 glioblastoma cell line, further confirming NRP1 as a miR-148a target." (PMID 26097868, 2015). "Of note, Nrp1 may be a useful target for therapy in glioblastoma, melanoma and some forms of leukemia." (PMID 22948112, 2012). "Notably, a synthetic peptide derived from the transmembrane segment of Nrp1 disrupted its coreceptor functions and showed therapeutic benefit in a glioblastoma model." (PMID 22948112, 2012). "While the exact composition of the secretome is largely unknown, related research has identified of insulin-like and opioid growth factors or proteins such as ADAM9, cathepsin B and neuropilin-1 as key components of the secretome of head and neck tumor or glioblastoma cells." (PMID 38092866, 2023). "Furthermore, extensive work highlighted the functional action of NRP1 on glioblastoma expansion." (PMID 36204684, 2022). "The iRGD peptide binds to αv integrins and neuropilin-1 (NRP-1), which is overexpressed in glioblastoma and other brain cancers, significantly enhancing the cellular uptake of therapeutic agents." (PMID 40761875, 2025).
glioblastoma (continued). "We have developed peptides combined with a photosensitizer to target NRP1 in the context of photodynamic therapy (PDT) to detect and treat glioblastoma." (PMID 37513474, 2023). "We also assessed the expression of the NRP1 protein by western blotting and VEGF-A by ELISA in other human cancer cell lines: PC3M, prostate cancer and U87MG, glioblastoma." (PMID 26209534, 2015). "Brain capillary endothelial cells express certain receptors—such as the TFR, neuropilin-1, low-density lipoprotein receptor-related protein, and N-acetylcholine receptor—on the BBB and glioblastoma multiforme cells, while these receptors are either minimally expressed or absent in normal tissues." (PMID 40140588, 2025). "In agreement with previous studies, NRP1 expression was over-represented in glioblastoma patients, as opposed to non-tumor brain tissue." (PMID 36204684, 2022). "Hence, we screened a panel of cells lines representing renal cancer (CAKI‐1, CAKI‐2, ACHN), bladder cancer (UC13, T24), and glioblastoma (U87MG), for expression of SEMA3C, EGFR, MET, Plexin B1, Plexin D1, NRP1, and NRP2." (PMID 29348142, 2018).